DUSP3 (dual specificity phosphatase 3)
Diseases named in the same sentence as DUSP3 in open-access papers (continued):
Sharing a sentence is not in itself a finding about the gene and the disease.
Insulin resistance (1 paper, 2021). Increased resistance towards insulin, that is, diminished effectiveness of insulin in reducing blood glucose levels. "While aging, DUSP3-KO mice became obese, exhibited insulin resistance, NAFLD and associated liver damage." (PMID 33712680, 2021). "Though, the HOMA-IR, which assesses insulin resistance from fasting glucose and insulin levels, was significantly higher in DUSP3-KO compared to WT mice under both CD and HFD and all time points analyzed." (PMID 33712680, 2021). "The insulin resistance observed in DUSP3-KO mice suggests that this phosphatase could play a role in insulin receptor (IR) signaling." (PMID 33712680, 2021). "We therefore investigated whether DUSP3 KO could exacerbate HFD-induced insulin resistance." (PMID 33712680, 2021). "Despite the observed insulin resistance in the KO mice, under CD, glucose homeostasis was not altered by DUSP3 deletion as assessed by the OGTT assay." (PMID 33712680, 2021).
ischemia (1 paper, 2025). A hypoperfusion of the BLOOD through an organ or tissue caused by a PATHOLOGIC CONSTRICTION or obstruction of its BLOOD VESSELS, or an absence of BLOOD CIRCULATION. "Genes associated with the stress-activated MAPK pathway—such as Dusp3, Dusp10, Dusp14, Junb, and Fos—were also specifically upregulated after ischemia, which may enable astrocytes to manage heightened stress signals, regulate inflammatory responses, and initiate repair mechanisms." (PMID 40618091, 2025).
liver disorder (1 paper, 2021). A disease involving the liver. "However, DUSP3-KO mice developed fatty liver, a prevalent complex disease that may lead to severe liver disorders." (PMID 33712680, 2021).
liver fibrosis (1 paper, 2022). "Among all these analyzed DUSPs, DUSP3, DUSP8, DUSP12, DUSP14, DUSP16, DUSP22, and DUSP26 were significantly decreased in the liver of NASH patients with obvious hepatocyte ballooning, severe inflammatory infiltrate, and pattern of liver fibrosis compared with the normal individuals." (PMID 36209205, 2022).
lung squamous cell carcinoma (1 paper, 2022). "Low DUSP3 expression is also observed in lung squamous cell carcinoma, which does not have EGFR mutation." (PMID 35705979, 2022).
lymph node metastasis (1 paper, 2021). "In the same study, upregulated miR-1915 was positively correlated with lymph node metastasis, and its ectopic expression increased the activity of ERK1/2 through repression of DUSP3." (PMID 34680382, 2021).
osteosarcoma (1 paper, 2025). A usually aggressive malignant bone-forming mesenchymal neoplasm, predominantly affecting adolescents and young adults. "Overall, these results show that DUSP3 is downregulated in osteosarcoma and that lower expression of the protein is linked to poorer patient outcomes." (PMID 39744427, 2025). "In this work, the underlying molecular mechanisms of DUSP3's effects on osteosarcoma biological behavior were examined." (PMID 39744427, 2025). "Inhibition of the STAT3/SOX2 signaling axis dramatically reduced the DUSP3 downregulation-promoting effects on osteosarcoma cell proliferation, migration, and invasion." (PMID 39744427, 2025). "Our results demonstrated a drop in the expression levels of N-cadherin and Vimentin, whereas there was an upregulation of E-cadherin, indicating that osteosarcoma cell invasion, migration, and proliferation are hampered by DUSP3 overexpression." (PMID 39744427, 2025). "It was observed that the osteosarcoma tissues had a decreased level of DUSP3 protein expression in comparison to the adjacent tissues." (PMID 39744427, 2025). "EdU staining and CCK-8 assays suggested that DUSP3 downregulation significantly promoted osteosarcoma cell proliferation." (PMID 39744427, 2025). "The CCK-8 assay suggested that DUSP3 upregulation downregulated the OD450 value of osteosarcoma cells." (PMID 39744427, 2025). "DUSP3 overexpression group demonstrated a remarkable reduction in lung metastases, as observed by visual observation and hematoxylin-eosin staining, suggesting that the overexpression of DUSP3 significantly inhibited lung metastasis in osteosarcoma." (PMID 39744427, 2025). "The protein levels of DUSP3 in twelve pairs of human osteosarcoma and paraneoplastic tissue samples were measured using western blot analysis." (PMID 39744427, 2025). "In an animal model, we administered subcutaneous injections of 143B osteosarcoma cells overexpressing DUSP3, and the results indicated that the overexpression of DUSP3 impaired osteosarcoma growth." (PMID 39744427, 2025). "ROC curves were plotted based on TCGA data, revealing that DUSP3 is a meaningful prognostic marker in osteosarcoma (AUC=0.725)." (PMID 39744427, 2025). "Collectively, our results demonstrated that DUSP3 regulates the stemness of osteosarcoma cells through the EGFR/STAT3/SOX2 axis." (PMID 39744427, 2025). "DUSP3 impairs osteosarcoma cells proliferation, migration, invasion, and stemness through regulating the EGFR/STAT3/SOX2 axis." (PMID 39744427, 2025). "Our results demonstrated that DUSP3 overexpression attenuated the migratory capability of osteosarcoma." (PMID 39744427, 2025). "We then established a nude mouse transplantation tumor model to examine the in vivo effects of DUSP3 on osteosarcoma." (PMID 39744427, 2025). "The CCK-8 assay indicated that DUSP3-mediated stemness regulated the sensitivity of osteosarcoma cells to cisplatin, suggesting that DUSP3 negatively regulates osteosarcoma cells stemness, thus improving their sensitivity to cisplatin." (PMID 39744427, 2025). "The findings demonstrated that DUSP3 was highly accurate in predicting the outcome of osteosarcoma patients, and that patients with low expression of DUSP3 had a less favorable prognosis." (PMID 39744427, 2025). "Through modulating the EGFR/STAT3/SOX2 axis, DUSP3 restrains osteosarcoma cell growth, migration, invasion, and stemness." (PMID 39744427, 2025). "We further investigated the specific molecular mechanisms by which DUSP3 affects osteosarcoma cell genesis, development, and stemness." (PMID 39744427, 2025). "We found that DUSP3 overexpression significantly inhibited the progression of osteosarcoma cells, whereas its knockdown showed the opposite effect." (PMID 39744427, 2025). "By combining the obtained data, we found that DUSP3 and DUSP15 were differentially expressed in osteosarcoma and associated with patients' prognosis." (PMID 39744427, 2025).
osteosarcoma (continued). "In conjunction with our earlier in vitro research, we can infer that DUSP3 inhibits osteosarcoma development and lung metastasis in vivo through regulating EGFR/STAT3/SOX2 axis." (PMID 39744427, 2025). "We found that DUSP3 affected osteosarcoma proliferation, migration, and invasion by regulating the Epidermal Growth Factor Receptor (EGFR)/STAT3/SOX2 axis." (PMID 39744427, 2025). "DUSP3 overexpression dramatically reduced osteosarcoma cell invasion in the transwell invasion assay, as evidenced by the fact that LV-DUSP3 group cells invaded less than LV-control group cells." (PMID 39744427, 2025). "The impact of DUSP3 on osteosarcoma biological behavior was evaluated using CCK-8, wound-healing, transwell invasion, and tumor sphere formation assays." (PMID 39744427, 2025). "This study investigated the effects of DUSP3 on the biological behavior of osteosarcoma and its potential mechanisms." (PMID 39744427, 2025). "Functional assays showed that the knockdown or upregulation of DUSP3 in osteosarcoma cells significantly affected their proliferation, migration, invasion, and stemness." (PMID 39744427, 2025). "DUSP3 is downregulated in osteosarcoma and its lower expression indicates poor patient outcomes." (PMID 39744427, 2025). "We then hypothesized that DUSP3, which is strongly correlated with the prognosis of osteosarcoma patients, may influence osteosarcoma cells' biological activities." (PMID 39744427, 2025). "Similarly, following DUSP3 knockdown, osteosarcoma cells' capacity to migrate and invade was noticeably increased in the wound-healing and transwell invasion experiments." (PMID 39744427, 2025). "Given that overexpression of DUSP3 restrains the progression of osteosarcoma, we hypothesized that silencing DUSP3 might have the opposite effect." (PMID 39744427, 2025). "Our research identified DUSP3 as a tumor suppressor gene in osteosarcoma." (PMID 39744427, 2025). "After applying the molecular docking technique and referring to several studies, we speculated that DUSP3 affects the stemness of osteosarcoma cells by regulating EGFR." (PMID 39744427, 2025). "Furthermore, we found that treatment with Stattic significantly attenuated the promoting effects of DUSP3 knockdown on osteosarcoma cell proliferation, migration, invasion, and stemness." (PMID 39744427, 2025). "To investigate the specific mechanisms, we used molecular docking techniques and found that EGFR might interact with DUSP3 and regulate osteosarcoma stemness." (PMID 39744427, 2025). "Despite DUSP3 research in other fields has progressed, its mechanism in osteosarcoma is still unknown." (PMID 39744427, 2025). "This present study found a decreased DUSP3 expression in human osteosarcoma tissues, and DUSP3 may function as an independent prognostic factor in osteosarcoma patients." (PMID 39744427, 2025). "To test this hypothesis, we constructed osteosarcoma cell lines stably transfected with DUSP3 knockdown or overexpression." (PMID 39744427, 2025). "Given that CSCs promote tumorigenesis, metastasis, and chemoresistance 21, 22, we further investigated whether DUSP3-mediated stemness influences the sensitivity of osteosarcoma cells to chemotherapy drugs." (PMID 39744427, 2025). "Similarly, STAT3 inhibition significantly altered the stemness-promoting effect of DUSP3 knockdown in osteosarcoma cells." (PMID 39744427, 2025). "Additionally, we investigated the effect of DUSP3 overexpression on the distant metastasis of osteosarcoma in vivo using a mouse lung metastasis model by injecting stably transfected osteosarcoma cells into mice through the tail vein." (PMID 39744427, 2025). "Additionally, we detected DUSP3 expression in osteosarcoma cell lines." (PMID 39744427, 2025). "Thus, our results indicated that DUSP3 regulates the STAT3/SOX2 axis in osteosarcoma." (PMID 39744427, 2025).
osteosarcoma (continued). "Additionally, we measured the tumorsphere formation ability in both cell lines to confirm whether this signaling axis regulates DUSP3-mediated osteosarcoma cell stemness." (PMID 39744427, 2025). "Therefore, we speculated that DUSP3 affects the stemness of osteosarcoma cells by regulating the EGFR/STAT3/SOX2 axis." (PMID 39744427, 2025). "We then screened for differential genes between high and low DUSP3 expression samples and performed KEGG (Kyoto Encyclopedia of Genes and Genomes) enrichment analysis, which showed that the JAK/STAT signaling pathway was closely associated with DUSP3 expression levels in osteosarcoma." (PMID 39744427, 2025). "We then speculated that DUSP3 regulates osteosarcoma cell stemness." (PMID 39744427, 2025). "Thus, osteosarcoma cells proliferate, migrate, and invade more readily when DUSP3 is silenced." (PMID 39744427, 2025). "Our results showed that DUSP3 binds to EGFR, inhibiting its phosphorylation, thereby regulating STAT3/SOX2 axis and affecting osteosarcoma cell stemness." (PMID 39744427, 2025). "DUSP3 overexpression significantly decreased the cell population in 143B and U2OS osteosarcoma cells; similarly, DUSP3 knockdown enriched the cell population." (PMID 39744427, 2025). "Therefore, targeting DUSP3 may serve as an effective therapeutic target in osteosarcoma treatment." (PMID 39744427, 2025). "However, the expression level of DUSP3 in osteosarcoma remains unclear." (PMID 39744427, 2025). "Targeting DUSP3 and the EGFR/STAT3/SOX2 axis may offer a new therapeutic approach for treating osteosarcoma." (PMID 39744427, 2025). "Additionally, on the population of osteosarcoma stem cells, EGFR overexpression significantly lessened the inhibitory effect of DUSP3 upregulation, whereas the promoting effect of DUSP3 downregulation on osteosarcoma stem cell population was significantly inhibited upon EGFR downregulation." (PMID 39744427, 2025). "RNA-seq technology was applied to 143B osteosarcoma cells with or without DUSP3 overexpression." (PMID 39744427, 2025). "Transcriptome sequencing revealed that DUSP3 expression level was closely related to the STAT3/SOX2 signaling pathway, which may be the specific mechanism by which DUSP3 restrains the malignant behaviors of osteosarcoma." (PMID 39744427, 2025).
cancer (19 papers, 2008 to 2025). A tumor composed of atypical neoplastic, often pleomorphic cells that invade other tissues. "It is likely that loss of DUSP3 contributes more than enhancing receptor tyrosine kinase (RTK) signaling during cancer progression." (PMID 35705979, 2022). "In this study, we found that TJ was defective in DUSP3-null cells, suggesting a novel mechanism by which DUSP3 deficiency participates in cancer progression." (PMID 35705979, 2022). "Three dmCGs with MD > 20% were identified which were associated with HOXA5, further RYR1, known to code for a ryanodine receptor in skeletal muscles and DUSP3, which is implicated in cancer and negatively regulates members of the mitogen-activated protein (MAP) kinase superfamily." (PMID 33547267, 2021). "In addition, DUSP3 has been implicated in human cancer, though it has been alternatively described as having tumor suppressive and oncogenic properties." (PMID 26305674, 2015). "The first study implicating DUSP3 in cancer showed that DUSP3 KD in HeLa cells, leads to cell cycle arrest at both the G1-S and G2-M transitions, and induces the initial signs of cellular senescence." (PMID 40943262, 2025). "Because of its shallow and broad catalytic pocket, DUSP3 has a diversity of substrates and acts as a central regulator of a variety of biological processes, including cancer." (PMID 39849581, 2025). "The role of DUSP3 and related molecular mechanisms involved in cancer development deserve more investigations." (PMID 35705979, 2022). "Vaccinia-H1 Related (VHR) dual-specificity phosphatase, or DUSP3, plays an important role in cell cycle regulation and its expression is altered in several human cancers." (PMID 29020102, 2017). "It should be noted that increase of DUSP3 expression is reported in several types of cancer." (PMID 35705979, 2022). "KDM2A-catalyzed H3K36me2 demethylation occurred gene-specifically at the promoter region of cancer-related genes including dual-specificity phosphatase 3 (DUSP3), which in turn antagonized DUSP3-mediated ERK1/2 dephosphorylation and consequently promoted lung tumorigenesis." (PMID 30002791, 2018). "In this study, we provide evidences for an unexpected role of DUSP3 in cancer metastasis." (PMID 29020102, 2017). "The altered expression of DUSP3 in several human cancers and the newly discovered role of DUSP3 in EC tubulogenesis prompted us to investigate if in vivo DUSP3 deficiency could also lead to a decrease in neovascularization and angiogenesis." (PMID 24886454, 2014). "We detected the expression levels of the stemness markers including OCT4, SOX2, and Nanog, finding that DUSP3 upregulation significantly decreased their expression levels; conversely, DUSP3 downregulation resulted in a noticeably higher levels of cancer stemness markers." (PMID 39744427, 2025). "Although initially reported as a possible tumour-supporting signal in cervical cancer cells, DUSP3, mainly through the regulation of ERK1/2, emerges as an interesting signalling molecule in other types of cancer, such as BC, NSCLC, and HCC." (PMID 40943262, 2025). "On the other hand, the genes upregulated after G9a depletion include several tumor suppressor genes like dual specificity phosphatases (DUSP1, DUSP3 and DUSP5), which mediate MAP kinase dephosphorylation and are commonly repressed in many cancer cells." (PMID 25115793, 2014). "We report that the up-regulation of this phosphatase is mainly due to its post-translational stabilization in the cancer cell lines compared to primary keratinocytes rather than increases in the transcription of DUSP3 locus." (PMID 18505570, 2008).